UBE2F-SCLY (UBE2F-SCLY readthrough (NMD candidate))
Gene: Protein-coding gene on chromosome 2 (237,967,014 to 238,099,412, forward strand). Ensembl gene ENSG00000258984.
Genetic constraint (gnomAD): Missense variants: 95 observed, 162.34 expected, observed/expected ratio (o/e) 0.59, 90% interval 0.5 to 0.69. Synonymous variants: 42 observed, 60.91 expected, observed/expected ratio (o/e) 0.69, 90% interval 0.54 to 0.89.